RASD1 (ras related dexamethasone induced 1)
Diseases named in the same sentence as RASD1 in open-access papers (continued):
Sharing a sentence is not in itself a finding about the gene and the disease.
cancer (continued). "Results of external validation in eRic database showed the specific chromatin localization and target genes of the four key DEeRNAs (CCR1, CD3D, PHLDA1, and RASD1), as well as potential drugs that may target these DEeRNAs in different cancers." (PMID 36092920, 2022). "In this context, the question arises how hsa-miR-375/RASD1 interferes in the cancer pathway system." (PMID 33255991, 2020). "A variety of genes were identified as being altered in LN tissue samples due to RRV infection, including cancer-associated genes activation-induced cytidine deaminase (AICDA), glypican-1 (GPC1), CX3C chemokine receptor 1 (CX3CR1), and Ras dexamethasone-induced 1 (RasD1)." (PMID 32017809, 2020). "miR-375 promotes cancer cell proliferation through RASD1-ERα pathway." (PMID 22703336, 2012). "Similarly, RASD1 mRNA and protein are present in a variety of cancer types." (PMID 40362656, 2025). "Furthermore, RASD1 remains diploid in most cases, indicating that copy number variation may not be a significant determinant of RASD1 expression or its involvement in cancer development across various tumor types." (PMID 40362656, 2025). "RasD1 has also been found to be capable of inhibiting the growth of cancer cells, and thus, decreased expression of RasD1 in RM LN tissues after RRV infection could potentially promote increased B cell proliferation and the development of B cell abnormalities in RRV-infected RM." (PMID 32017809, 2020). "Thus, while RASD1 downregulation may be a common feature of these cancers, its functional relevance appears to be context-dependent, emphasizing the need for further studies to elucidate the underlying mechanisms governing its differential impact on cancer prognosis." (PMID 40362656, 2025). "The SPINK1 general cancer pathway and HGF signalling were activated in G3 cells in which the tumour malignancy‐related genes RASD1, PIK3R1, JUN, and FOS were significantly upregulated, indicating that G3 promotes malignant progression in GC." (PMID 35184420, 2022). "As demonstrated in the top DEGs, specifically cancer stem lineage clusters expressed high levels of stemness feature genes (MKI67, CD44, CD24, and PROM1) and key DEeRNAs (PHLDA1 and RASD1)." (PMID 36092920, 2022). "Among the cancer driver genes expressed in K-RMS-1 we found increments in the expression of BAX, RASD1, WT1, AKT1, cMYC and NOTCH." (PMID 30745580, 2019). "We further investigated the expression of key DEeRNAs between tumor and normal samples among different cancer types and identified that the expression level of CCR1, CD3D, PHLDA1, and RASD1 was significantly up-regulated in tumor tissue, as compared with normal tissue." (PMID 36092920, 2022). "Understanding these differences is crucial, as the presence or absence of RASD1 expression may differentially regulate cancer cell behavior and progression." (PMID 40362656, 2025). "The potential mechanism for the formononetin-ERβ axis to exert anti-cancer effects may be that formononetin acts on microRNA-375, RASD1, or ERα to form a negative feedback loop, but this requires further verification." (PMID 34513331, 2021). "Overall, the infrequent occurrence of copy number alterations and the absence of recurrent predicted loss-of-function mutations across various cancer types suggest that genetic alterations in RASD1 may not play a significant role in modulating RASD1 expression or activity in the cancers analyzed." (PMID 40362656, 2025). "Hence, modulation of NR4A1 and NR4A2 expression by Rasd1 and NonO could have a major impact on the circadian control, and disruption of this process can give rise to metabolic diseases and cancer development." (PMID 21915321, 2011). "However, the copy number of RASD1 remains diploid in most samples, suggesting that the variation in copy number may not be the main factor for regulating RASD1 expression in cancer." (PMID 40362656, 2025).
tumor (24 papers, 2007 to 2026). "In this USP8-mutated tumor, we identified an interesting somatic mutation in the gene RASD1, which is a component of the corticotropin-releasing hormone receptor signaling system." (PMID 28487882, 2017). "A novel mutation, p.K34M, in the GTP-binding region of RASD1 was identified in this tumor, at an allelic fraction (3%) indicative of a subclone with respect to cells containing USP8 p.P720R." (PMID 28487882, 2017). "The different allelic fractions between the USP8 and RASD1 somatic mutations in the studied tumor cells suggest that this ACTH-secreting tumor is genetically heterogeneous." (PMID 28487882, 2017). "Using genes with similar expression patterns to that of RASD1 sheds light on potential molecular mechanisms and pathways associated with RASD1 expression that may impact tumor biology." (PMID 40362656, 2025). "This epigenetic inactivation is associated with adverse clinical features and enhanced cell survival, supporting a tumor suppressor role for RASD1 in MM pathogenesis." (PMID 41627676, 2026). "Collectively, these findings offer valuable insights into RASD1′s potential role in tumor regulation." (PMID 40362656, 2025). "Subcutaneous xenograft assays in nude mice demonstrated that reduced tumor growth and decreased tumor weight were also partially reversed after RASD1 knockdown." (PMID 38902717, 2024). "This lncRNA can epigenetically repress Ras-related dexamethasone inducible 1 (RASD1) by recruiting LSD1 to the region of RASD1 promoter, ultimately promoting malignant behaviors of tumor cells." (PMID 35155211, 2021). "We found that CYP7A1, GINS2, and PDLIM3 were significantly up-regulated, and MYC, MAMDC4, ADAMTS1, THBS1, and RASD1 were significantly down-regulated in HCC tumor samples compared with normal samples using the TCGA dataset." (PMID 34777484, 2021). "We found that CYP7A1, GINS2, and PDLIM3 were significantly up-regulated, and MYC, MAMDC4, ADAMTS1, THBS1, and RASD1 were significantly down-regulated in HCC tumor samples compared to normal samples." (PMID 34777484, 2021). "At a later time point in the pathogenesis of the tumor, one of these USP8-mutant cells acquires a RASD1 mutation, resulting in a subclone of RASD1-mutant/USP8-mutant cells." (PMID 28487882, 2017). "Regarding individual gene expression during this recovery period, we noted significant downregulation of Pdk4 and Rasd1, both identified as inactivated tumor suppressor genes in a global DNA methylation study." (PMID 28575117, 2017). "Tumor-specific hypermethylation has also been found in the promoter regions of various tumor suppressors and other tumor-related genes, including BNIP3, DAPK and RASD1, which are associated with prognosis and drug resistance in MM." (PMID 23259664, 2012). "To explore possible tumor extrinsic and intrinsic factors by which RASD1 levels could potentially influence patient survival outcomes, we sought to compare immune cell infiltrates and gene set enrichments that were different between RASD1 high vs. low tumors." (PMID 40362656, 2025). "We acknowledge that this study cannot prove the molecular functions of RASD1 in tumor suppression." (PMID 40362656, 2025). "Overall, these findings suggest that RASD1 may modulate immune signaling and tumor suppressive pathways." (PMID 40362656, 2025). "Despite detectable protein expression in breast, lung, and prostate tissues, consistent tumor-suppressive effects are not observed, implying that additional context-specific factors may modulate RASD1′s role in tumor progression." (PMID 40362656, 2025). "Dexamethasone-induced Ras-related protein 1 (RASD1), a member of the Ras superfamily, is widely expressed across various tissues and is involved in inhibiting cell growth and inducing apoptosis, suggesting a potential role as a tumor suppressor." (PMID 40362656, 2025).
tumor (continued). "Using enrichment analysis, we identified several pathways that might be related to the tumor suppressor function of RASD1, such as the interleukin (IL)-4′s regulation of apoptosis." (PMID 40362656, 2025). "Collectively, these findings suggest a potential tumor-suppressive role for RASD1 in GC." (PMID 38902717, 2024). "In this study, we found that RASD1 functions as a tumor suppressor in GC." (PMID 38902717, 2024). "Moreover, KIAA1429 enhances the proliferation and metastasis of GC cells by downregulating the expression of RASD1, a tumor suppressor involved in the MAPK/ERK signaling pathway." (PMID 38902717, 2024). "To evaluate whether RASD1 functions as a tumor suppressor in GC, we firstly measured the RASD1 mRNA expression according to the TCGA database." (PMID 32651355, 2020). "Although there are still some controversies regarding the roles RASD1 played in carcinogenesis, many studies revealed that RASD1 could serve as a tumor suppressor in diverse malignancies." (PMID 32651355, 2020). "However, the GFP-labeled tumor cells invaded the brain much less extensively in the Lenti-RASD1 group than in the Lenti-Vector group, as evidenced by the decreased number of invading cells outside the tumor core in the Lenti-RASD1 group (P = 0.006)." (PMID 28600528, 2017). "Furthermore, the Reactome pathway analysis indicates that RASD1 and genes associated with RASD1 expression may be involved in the “Regulation of PTEN gene transcription” during tumor pathogenesis." (PMID 40362656, 2025). "The dot plots showed the proportion of cells expressing tumor stemness-related gene markers (CD44 and MKI67) and key DEeRNAs (PHLDA1 and RASD1) and their scaled relative expression level in 12 cell clusters." (PMID 36092920, 2022). "Known functions of both SOX18 and RASD1 are consistent with our finding, where SOX18 was suggested to be oncogenic while RASD1 was tumor suppressive." (PMID 34830961, 2021). "Our hypothesis is that under both these models, RASD1 is a contributor to cell proliferation and ACTH secretion, but occurs in a small subpopulation of the tumor cells." (PMID 28487882, 2017). "In the intracranial glioma xenograft model, the overexpression of RASD1 significantly reduced the number of tumor cells invading into the surrounding tissues without affecting the tumor size." (PMID 28600528, 2017). "The tumor volume was not significantly different between tumors derived from Lenti-Vector and Lenti-RASD1 U87 cells (P = 0.698)." (PMID 28600528, 2017). "As opposed to these structurally related molecules, RASD1 inhibits clonal cell expansion suggesting a tumor suppressive role." (PMID 26962366, 2016). "Importantly, high RASD1 RNA expression correlated with improved survival in KIRC, LGG, and PAAD and our finding suggests that this could potentially be due to increased infiltration of CD4+ T cells and myeloid dendritic cells in the tumor microenvironment." (PMID 40362656, 2025). "Finally, to investigate if methylation-mediated silencing of tumour suppressor genes negatively regulating RAS signalling pathway may account for functional activation of RAS, DNA methylation of RASSF1A and RASD1 promoters were studied by methylation-specific PCR (MSP)." (PMID 30201956, 2018).
infection (9 papers, 2018 to 2025). The state of being infected such as from the introduction of a foreign agent such as serum, vaccine, antigenic substance or organism. "Since viral genes barely have introns, the directionality of infection progression is driven by virus-induced host cell genes such as RASD1." (PMID 31653857, 2019). "An additional four genes were upregulated in ΔprgH STm infection and were involved in the regulation of glycolysis (PFKFB3) and cytokine signaling (SOCS3), and intracellular signaling (RASD1, TRAF3IP2)." (PMID 37854334, 2023). "To investigate the influence of RASD1 and RRAD on viral production, we depleted RASD1 and RRAD by small interfering RNA (siRNA) knockdown prior to infection, and observed increased virion production at 16 hpi, suggesting that both genes posses some antiviral activity." (PMID 31653857, 2019). "Two small GTPases, RASD1 and RRAD, were directly induced by the infection." (PMID 31653857, 2019).
cardiovascular disease (2 papers, 2014 to 2024). "Actually, bioinformatics and external validation suggest that downregulation of RASD1/NAMPT may be an important mechanism for the increased risk of cardiovascular disease in women with HCM." (PMID 39535387, 2024).
cardiac disease (1 paper, 2022). "Combined with the genome-wide association study (GWAS) analysis, cardiac disease-associated genes Rasd1, Thsd7a, Ednra, and Tns1 were identified." (PMID 35938163, 2022). "In heart disease, RASD1 was found to significantly inhibit the secretion of atrial natriuretic peptide (ANP) in HL-1 cells." (PMID 35938163, 2022).
RASD1 also shares sentences with these, for which no sentence is quoted: optic neuritis (3 papers); Anxiety (2); atherosclerosis (2); colorectal cancer (2); gastric tumor (2); hepatocellular carcinoma (2); liver cancer (2); melanoma (2); metabolic disease (2); renal cell carcinoma (2); Stroke (2); adenoma (1); Alzheimer disease (1); asthma (1); autoimmune disease (1); autoimmune encephalitis (1); breast tumors (1); Cerebral ischemia (1); colon adenocarcinoma (1); COVID-19 (1); Cushing syndrome (1); depression (1); endometrial cancer (1); endothelial dysfunction (1); esophageal carcinoma (1); glaucoma (1); glioblastoma (1); head and neck squamous cell carcinoma (1); Huntington chorea (1); Hypercalcemia (1).
A further 24 diseases each share a sentence with RASD1 in 1 paper.